TNF (tumor necrosis factor)
Diseases named in the same sentence as TNF in open-access papers (continued):
Sharing a sentence is not in itself a finding about the gene and the disease.
COVID-19 (continued). "The levels of proinflammatory cytokines/chemokines such as interleukin 6 (IL-6), IL-8, interferon gamma (IFN-γ)-induced protein 10 (IP-10), and tumor necrosis factor alpha (TNF-α) are markedly elevated in the sera of severe COVID-19 patients (4, –, 9)." (PMID 35856559, 2022). "Predictors of disease severity include ferritin, TNF-α, IL-8, IL-1β and IL-6, suggesting that hyperinflammation is driving COVID-19 severity and death." (PMID 35244141, 2022). "Anti-TNFα drugs neutralize a major component of the cytokine response that is part of the damaging excess inflammatory phase of COVID-19." (PMID 35757699, 2022). "Sodium pyruvate impairs inflammatory cytokine production (IL-6, IL-1β, and TNF-α) in macrophages during Influenza A virus infection and has been tested in clinical trials for acute COVID-19 and now Long COVID." (PMID 36070309, 2022). "Results demonstrate that TNF-α, seen elevated in severe COVID-19 cases, have beensignificantly reduced (P = 0.021; P < 0.001) over a 3–4-month MD interventionfor overweight/obese adults." (PMID 36131504, 2022). "COVID-19 vaccine-induced antibody responses are reduced in patients with inflammatory bowel disease (IBD) taking anti-TNF or tofacitinib after two vaccine doses." (PMID 36088954, 2022). "AM3 supplementation improves COVID-19 outcomes by decreasing the systemic levels of IL-6, TNF-α, CRP and ferritin and the enzymes ALT, AST, LDH, CK, and MB." (PMID 36458163, 2022). "Some of these biological therapies, such as IL-6, IL-1 and TNF inhibitors, showed promising results also in COVID-19 patients." (PMID 35563218, 2022). "Inflammatory mediators such as IFN-γ, tumor necrosis factor (TNF), IL-2, IL-6, and IL-10 were also elevated in COVID-19 patients, and higher levels were reported in the severe cases." (PMID 35330388, 2022). "It has been reported that the prevalence of severe cases of COVID-19 was lower in patients with anti-TNF-α therapy compared to patients treated with steroids." (PMID 36016267, 2022). "Currently, a clinical trial comprised of COVID-19 patients evaluating adalimumab, an anti-TNF-α drug, has been registered in China (ChiCTR2000030089)." (PMID 35223745, 2022). "In this study, we also found an increase in IFN-γ, TNF-α, IL-1 β, IL-6, and IL-10 in the V-COVID-19 group, which included patients that required hospitalization." (PMID 36497139, 2022). "More specifically, through clustering analysis, the down-regulated DEPs of the si-HAPLN1 group were enriched in S. aureus infection, SLE, TNF signaling pathway, COVID-19, and ribosome." (PMID 35720292, 2022). "Cao and colleagues found that TNF-α plays a role in endometriosis, and its expression is increased in tissues of patients with COVID-19." (PMID 36361745, 2022). "In spite of potential chronic activation in HD, our correlational evidence suggests an intact IFNγ/TNFα-IDO-Kyn axis sensitive to COVID-19." (PMID 36430566, 2022). "The plasma concentration of TNFα correlated with the surface expression of CD47 when the COVID-19 and Control groups were pooled for analysis, whereas the concentration of IL-6 in plasma did not correlate with CD47 expression in any group." (PMID 36466824, 2022). "Within anti-TNF-α-treated patients, COVID-19 asymptomatic subjects had a trend to higher CD8+ total memory GZMB/K+, memory, and class-switched B cells, while TH1 and CD8+ CD27+ GZMB/K+ cells were comparable in symptomatic and asymptomatic subjects." (PMID 35757699, 2022). "It is already known that cytokine storm (hypercytokinemia) resulting in increased systemic inflammation with high levels of IL-6, IL-1β, and TNFα is induced by viral infections, including influenza A and COVID-19." (PMID 36504633, 2022). "The results showed that the level of pro-inflammatory cytokines, TNF-α, IL-6, IL-8, and IL-1β were significantly elevated in severe COVID-19 patients, but the alarmin molecules IL-1α and HMGB1 were marginally higher." (PMID 36585712, 2022).
COVID-19 (continued). "Other therapeutic monoclonal antibodies are directed at proinflammatory cytokines (IL-6, IL-1β, TNF and GM-CSF) to mitigate cytokine storm syndrome (CSS) that is the frequent cause of fatal acute respiratory distress syndromes (ARDS) in COVID-19 patients." (PMID 35743031, 2022). "Six of nine patients who had COVID-19 after vaccination were receiving anti-tumor necrosis factor (TNF)-α antibodies." (PMID 35089397, 2022). "We found that plasma exosomes from COVID-19 patients upon admission (E) significantly stimulated the production of cytokines and chemokines, including IL-6, IL-8, and TNF-α, compared with those from the same patients later in their hospitalization." (PMID 36526691, 2022). "As TNF-α overproduction has been documented in COVID-19, the efficacy and clinical benefits of anti-TNF antibody therapy have been investigated." (PMID 35464491, 2022). "The anti-TNF treatment results have been promising in multi-national clinical trials, with patients showing less COVID-19-related mortality in several clinical studies done in Spanish/Italian patients with rheumatic diseases." (PMID 36672763, 2022). "The proposed pathogenesis for this common coexistence is elevated levels of IL-6, tumor necrosis factor α (TNF α), and granulocyte-macrophage colony-stimulating factor resulting in COVID-19 induced cytokine storm." (PMID 35865966, 2022). "Patients with severe COVID-19 reportedly have high levels of proinflammatory cytokines such as IL-2R, IL-6, and TNF-α." (PMID 36246680, 2022). "A cytokine storm in Coronavirus-disease-19 (COVID-19) is accompanied by the rapid release of pro-inflammatory cytokines IL-6 and TNF-α." (PMID 35651623, 2022). "Among them, pathways in cancer and the TNF signaling pathway are the core pathways followed by five anti-COVID-19 core targets." (PMID 35992697, 2022). "Biologics such as anti-TNF therapies, ustekinumab, and vedolizumab should be delayed for two weeks to monitor for development of symptoms of COVID-19." (PMID 35496814, 2022). "The surviving severe COVID-19 patients showed significantly lower circulating concentrations of TNFα, TGFα, IL-10, sRAGE, sTNF-RI and sTNF-RII compared to the non-survivors (p = 0.001, p = 0.031, p < 0.0001, p < 0.0001, p = 0.001 and p < 0.0001, respectively)." (PMID 36142255, 2022). "Patients with COVID-19 residing at high-altitude tend to have higher levels of inflammatory cytokines compared to patients living at sea level, particularly IL-6 and TNF-α." (PMID 35090394, 2022). "Higher concentrations of serological TNF-α, IL-6, MIP1b and IL-4 were observed within the P-COVID-19+ group, while cytokines and chemokines secreted by peripheral leucocytes in response to LPS, IL-6 or PMA-ionomicin were similar among the groups." (PMID 35901034, 2022). "SDC-1 reflects the endothelial damage directly and demonstrates the TNF-α -induced glycocalyx damage since the SDC-1/TNF-α ratio increases as the COVID-19 severity increases." (PMID 36556051, 2022). "The excessive inflammatory response characterized by the upregulated IL-6 and TNF-α is a typical immune disorder in patients with severe COVID-19." (PMID 35685940, 2022). "Observational data from patients already on anti-TNF therapy show a reduced rate of COVID-19 poor outcomes and death compared with other immune-suppressing therapies." (PMID 36380355, 2022). "The uncontrolled release of IL-6, IFNγ, and TNF-α can result in a downstream cascade of cytokine and cellular responses that further contribute to disease severity in both COVID-19 and malaria." (PMID 36415655, 2022). "TNF at the transcriptional level was decreased in COVID-19 patients as compared to HD (p < 0.0001), and this mRNA level was maintained for each type of COVID-19 severity (p < 0.0001)." (PMID 34445140, 2021). "PIMS-TS children had significantly elevated levels of cytokines, IFNγ, IL-2, TNFα, IL-1α, IFNα, IFNβ, IL-6, IL-17A, GM-CSF, IL-10, IL-33 and IL-Ra in comparison to COVID-19, seropositive and control children." (PMID 33813138, 2021).
COVID-19 (continued). "This is one of the most important reasons suggesting that trials for anti-TNF therapy should include the measure of TNF and its receptors to direct the efforts in developing the best alternative schemes of treatment for COVID-19." (PMID 34445140, 2021). "Another study observed elevated levels of IL-6 and TNF-α in children with COVID-19, as compared to those in controls; however, the increased levels of these cytokines lacked any correlation with disease severity." (PMID 34835108, 2021). "Overall, our study showed that high levels of immune-inflammatory markers (IL-6, IL-8, IL-10 and TNF-a) were all strong predictors of severe COVID-19 by ROC analysis." (PMID 34488665, 2021). "Detailed information, including drug dosage, drug combination, and classification of psoriasis, was insufficient.Anti-TNF agents seemed to play a protective role in COVID-19 among patients with immune-mediated inflammatory diseases." (PMID 34335579, 2021). "Inhibition of PANoptosis protects mice from pathology and death caused by TNF-α and IFN-γ, which resemble COVID-19’s tissue damage and inflammation." (PMID 34946543, 2021). "TMPRSS2 is an enzyme that primes the spike S protein of the SARS-CoV-2 virus to promote virus entry, IL6 and TNF are pro-inflammatory cytokines that are found generally elevated in severe COVID-19 patients." (PMID 34109284, 2021). "One of the most prominent characteristics of severe COVID-19 is the massive release of a wide range of cytokines, such as TNF, interferon γ (IFN-γ) and IL-1, IL-6, and IL-18, which characterizes the cytokine storm observed in SARS-Cov-2 infected patients." (PMID 34977191, 2021). "In this study, levels of serum proinflammatory cytokines increased in most patients with COVID-19, and the level of most cytokines (e.g., TNF-α, IL-6, and IL-8) were greatly higher in critical patients than in severe cases." (PMID 34725309, 2021). "Chronic inflammation and increased cytokine production, like TNF-α, IL-6, and CCL5, are critical features of COVID-19 patients, which suggests that they cause severe lung injury, multi-organ failure, and poor prognosis." (PMID 33804769, 2021). "IL-2 was lower in COVID-19 patients than in healthy individuals, while IL-4, IL-6, CCL2, IFN-γ, and TNF-α were higher in COVID-19 patients than in healthy individuals." (PMID 34489974, 2021). "Another hallmark of severe COVID-19 is the cytokine storm associated with elevated levels of cytokines (IL1β, IL1Rα, IL2, IL6, IL7, IL10, G-CSF, TNFα), chemokines (IP10, MCP1, MIP1α) and endogenous neutrophil calprotectin." (PMID 34867943, 2021). "Mono was reported to persist up to 16 months post infection among post-acute sequelae SARS-CoV-2 or long-COVID-19 patients in the presence of TNF." (PMID 34867943, 2021). "In brief, although observational data on anti-TNF use that must be interpreted with caution are suggestive of a therapeutic benefit in patients with COVID-19, results of randomized controlled trials (RCTs) are needed to confirm this benefit." (PMID 34803441, 2021). "This sex-specific anti-inflammatory effect resulted from the greater reduction of IL-6 and TNF-α, was possibly crucial to COVID-19 severity." (PMID 34373739, 2021). "Nevertheless, IL-1 and TNF-α, cytokines that are markedly increased in COVID-19 patients, also induce endothelial cells to synthesize tissue factor (TF), the primary initiator of coagulation." (PMID 34977191, 2021). "We attributed the alteration of CD90 activity to the high expression of proinflammatory cytokines, such as IL-1β and TNFα, which are commonly increased in COVID-19 patients." (PMID 34746417, 2021). "Since acute lung injury is also a characteristic finding in COVID-19, this study also supports the possible benefit of anti-TNF agents in the treatment of the cytokine storm of COVID-19." (PMID 34803441, 2021).
COVID-19 (continued). "High levels of proinflammatory cytokines (e.g., IL-12, IL-7, monocyte chemoattractant protein-1 [MCP-1], TNF-α, and granulocyte colony-stimulating factor) are essential in the pathogenesis of COVID-19." (PMID 34725309, 2021). "The cytokine profiles in severe COVID-19 patients are similar to those in cytokine release syndromes, with increased production of cytokines such as interleukin (IL)-6, IL-7 and tumor necrosis factor (TNF) and also CXC-chemokine ligand 10 (CXCL10)." (PMID 33995267, 2021). "COVID-19 is also characterized by a “cytokine storm” with increased levels of pro-inflammatory cytokines in the blood, such as IL-1β, TNF-α, IL-6, IL-12, and we detected increased IL-1β, IL-6, IL-12, IL-23, and IL-27 in the serum following ORN06 aspiration." (PMID 33481950, 2021). "Assessment of infection-related biomarkers (CRP, ESR) and cytokine profile (IL-2R, IL-6, IL-8, IL-10, IL-1β, TNF-α, procalcitonin) on admission showed a proinflammatory state in hemodialysis patients with COVID-19." (PMID 33967613, 2021). "Investigators discovered a negative correlation between T cell numbers and the concentration of cytokines including interleukin-6 (IL-6), IL-10, interferon-γ (IFN-γ), and tumor necrosis factor-α (TNF-α) in COVID-19 patients." (PMID 34766001, 2021). "Common coagulation-related observations in COVID-19 patients include increased D-dimer level, decreased platelet count, increased interleukin level, abnormal tumor necrosis factor, increased lactate dehydrogenase, and prolonged prothrombin time (PT)." (PMID 34321077, 2021). "Patients suffering from severe COVID-19 have been observed to show higher levels of serum proinflammatory cytokines such as interleukin (IL)-6 (IL-6), IL-1 and tumor necrosis factor (TNF)-α, also known as ‘cytokine storm’ or ‘inflammatory storm’." (PMID 33480978, 2021). "It is also noteworthy that IFNγ- and TNFα-producing MAIT cells were more numerous in COVID-19 patients who died compared with those who recovered." (PMID 34638950, 2021). "Higher levels of IL-6 and TNF-alpha were found in the COVID-19 group compared to other infections and control groups (p = 0.014 and p = 0.001, respectively)." (PMID 34578450, 2021). "Inhibition of PANoptosis protects the animal model from pathology and death caused by TNF-α and IFN-γ, which resemble COVID-19’s tissue damage and inflammation." (PMID 34946543, 2021). "Disease severity and death of COVID-19 patients have been correlated to the elevated expression of IL-6 and TNFα." (PMID 34866574, 2021). "TNF-α and IL-10 directly correlate with COVID-19 severity and are synonymous with patient deterioration." (PMID 34368648, 2021). "Considering the role of TNF-α in triggering COVID-19-related cytokine storm syndrome (COVID-CS) and ARDS, it is necessary to develop new approaches for anti-TNF therapy." (PMID 33566210, 2021). "In agreement, we found enhanced production of IL-6 and TNF-α by monocytes and NK cells of COVID-19 patients once treated with the recombinant human Gal-9 in vitro." (PMID 33947753, 2021). "On the other hand, other authors suggest an inflammatory underlying mechanism of anosmia, and in this line a previous study found that a proinflammatory cytokine -TNF alpha- was higher in the olfactory mucosa in patients with COVID-19." (PMID 34088273, 2021). "In a subgroup of 49 available plasma samples from COVID-19 patients, collected at a median of 2.8 (2.1–3.7) months after baseline, circulating levels of PAMPs (16S rDNA), DAMPs (mtDNA), and cytokines (IL-6, TNF-α, and IL-10) were quantified." (PMID 34659235, 2021). "Serum TNF levels were previously found to be markedly elevated in patients with COVID-19 and positively correlated with disease severity and death, suggesting the potential of TNF inhibitor for COVID-19." (PMID 34959657, 2021).
COVID-19 (continued). "COVID-19 patients had unique hyperinflammatory signatures across all types of peripheral blood immune cells, particularly increases in TNF- and IL-1β-driven inflammatory responses, whereas IFN responses were dominant in severe influenza patients." (PMID 33953323, 2021). "The linear multiple regression model was calculated to predict the levels of IL-33 based on COVID-19 severity, IL-6, IL-1β, IL-12, TNF-α, and IL-23." (PMID 34917631, 2021). "Many inflammatory biomarkers, such as interleukin (IL)-2, IL-6, IL-10 and tumor necrosis factor, were found higher in COVID-19 patients with severe disease, compared with those with mild or moderate disease." (PMID 34640618, 2021). "It is noteworthy that IL-6 and TNF-α are significantly elevated in patients with severe COVID-19, and that LIF is an IL-6 cytokine that can activate the JAK/STAT and MAP kinase pathways." (PMID 34395311, 2021). "In order to determine the relationship between IL-33 and proinflammatory mediators in all stages of COVID-19, we analyzed the ratio of the systemic values of IL-33 with the values of TNF-α, IL-1β, IL-6, IL-12, and IL-23." (PMID 34917631, 2021). "The majority of COVID-19 patients had normal levels of TNF-α (40/52, 76.9%), IL-2 (47/52, 90.4%) and IL-4 (36/52, 69.2%)." (PMID 34123873, 2021). "Studies have shown that the levels of various cytokines such as IL-2R, IL-6, IL-10, IL-2, IL-7, GCSF and TNF-α are significantly higher in patients with severe COVID-19 compared with patients who have a mild disease." (PMID 34490065, 2021). "Overall, pronounced inhibition of TNFα and IL-6 is the most important finding, as these molecules are currently considered to be the key actionable targets in COVID-19 cytokine storm and ARDS." (PMID 33465050, 2021). "The hyperinflammatory response in COVID-19 is characterized by elevated levels of serum TNF-α, IL-6, and to a lower level IL-1A since this cytokine has a short serum half-life." (PMID 33995033, 2021). "Cytokine excess, in particular IL-2, IL-4, IL-6, TNF-α, and IFN-Ɣ are known drivers of the overactive inflammatory response and associated COVID-19 severity." (PMID 34675810, 2021). "Cytokine storm was well-described in patients with severe COVID-19, displaying significantly elevated serum levels of IL-6, IL-8, IL-10, IL-2R, and tumor necrosis factor-alpha (TNF-α) compared with those mild and moderate patients." (PMID 35155477, 2021). "Proinflammatory cytokines in the blood were found to be upregulated in COVID-19 patients, including interleukin- (IL-) 1, IL-6, tumor necrosis factor (TNF), and interferon γ." (PMID 34580601, 2021). "A detailed assessment of the cytokine profile in severe cases of COVID-19 indicates that some cytokines and chemokines are strongly elevated, such as interleukin (IL)-6, IL-8, and tumor necrosis factor (TNF)." (PMID 33979301, 2021). "A key characteristic of severe COVID-19 is the dysregulation of inflammatory pathways with the increased production of cytokines such as interleukine-6 (IL-6) and tumor necrosis factor-α (TNF-α)." (PMID 34960708, 2021). "Most patients with severe COVID-19 exhibited large amounts of pro-inflammatory cytokines and chemokines, such as IL-2, IL-6, IL-7, TNF-α, granulocyte colony stimulating factor (GCSF), CXC-chemokine ligand 10 (CXCL10), CC-chemokine ligand 2 (CCL2), and CCL3." (PMID 33987176, 2021). "Dysregulated immune response and cytokine storm, with elevated levels of IL-6, IL-10, and TNF-α, and lymphopenia, correlated with worse outcomes in COVID-19 patients." (PMID 34439920, 2021). "It has been revealed that patients with severe COVID-19 present higher levels of IL-2, IL-6, IL-7, IL-10, and TNF-α than the patients with mild and moderate disease." (PMID 34088317, 2021). "JAK2 inhibitor Fedratinib has been proved to inhibit the production of several Th17 cytokines, including IL-6, IL-17, IL-21, IL-22, IL-1β, and TNF-α, thereby preventing Th17-related cytokine storm in COVID-19 patients." (PMID 34650550, 2021).